MYCN (MYCN proto-oncogene, bHLH transcription factor)
Diseases named in the same sentence as MYCN in open-access papers (continued):
Sharing a sentence is not in itself a finding about the gene and the disease.
neuroblastoma (continued). "While MYCN expression is an important contributing factor to heterogeneity in the natural history of neuroblastoma (NBL), a mechanistic understanding of this often mutationally quiet tumor has remained elusive." (PMID 37183823, 2023). "Aberrant MYCN amplification was previously considered as a driving event of high-risk neuroblastoma." (PMID 37064095, 2023). "Paradigmatic is the observation that a subgroup of high-risk neuroblastoma patients having mostly unfavourable outcome were characterized by TERT rearrangements or by MYCN amplified tumours, both inducing massive transcriptional upregulation of the TERT gene." (PMID 38033865, 2023). "Malignant progression, therapy resistance and disease relapse in neuroblastoma are associated with an undifferentiated phenotype, which is linked to the broad activation/repression of MYCN/c-MYC target genes." (PMID 37361539, 2023). "Human primary tumor cells derived from patients with MYCN-amplified high-risk neuroblastoma were implanted orthotopically in the retroperitoneal periadrenal space of mice, which modeled the typical anatomic site and microenvironment of human disease." (PMID 37874199, 2023). "Kelly cells have one of the highest expressions of MYCN in human neuroblastoma cell lines, and their survival hallmark depends on MYCN-related transcription." (PMID 38004392, 2023). "IGF2BP1 is upregulated in higher-risk clinical neuroblastoma groupings, including MYCN-amplified (MNA) or INSS-4 (International Neuroblastoma Staging System) tumors." (PMID 37246217, 2023). "We analyzed samples from 20 patients with different neuroblastoma subtypes (11q-deleted and MYCN Proto-Oncogene (MYCN)-amplified high-risk tumors, and low-risk)." (PMID 37731742, 2023). "MYCN amplification (MNA) is a defining feature of high-risk neuroblastoma (NB) and predicts poor prognosis." (PMID 37611092, 2023). "The risk classification of neuroblastoma is based on a comprehensive assessment of the child’s age, MYCN gene amplification, and 11q chromosome aberrations." (PMID 36770809, 2023). "In whole genome sequencing analyses of high-risk neuroblastoma, MYCN amplifications (37%), TERT rearrangements (23%), and recurrent ATRX deletions (11%) were identified." (PMID 37190157, 2023). "Amplification of the MYCN gene has been identified in nearly half of all high-risk cases of Neuroblastoma." (PMID 37314524, 2023). "In a previous publication from our group, with a totally different cohort of neuroblastoma patients, we already found that this variant was correlated with poorer overall survival in both normal and amplified MYCN patients." (PMID 36900216, 2023). "Whereas high-risk MYCN-amplified neuroblastomas were characterized by signs of replication slippage and stress, homologous recombination-associated signatures defined high-risk non-MYCN-amplified patients." (PMID 37868040, 2023). "Substitution of a T-containing allele for the G-containing allele at rs2168101 impairs the initiation of neuroblastoma in a MYCN-driven zebrafish model." (PMID 37183825, 2023). "While MYCN amplification is an accepted driver of adverse clinical outcome in patients with neuroblastoma, the molecular features defining high-risk neuroblastomas without MYCN amplification are not clearly understood." (PMID 37402719, 2023). "In neuroblastoma (NB), treatment and prognosis depend on the patient’s risk profile by age, evidence of amplification of the oncogene MYCN, distant metastases, and tumor grading." (PMID 37762918, 2023). "MYCN maps to the chromosome 2p24.3 region and gain of MYCN copy number variation is detected in about 25% high risk neuroblastoma." (PMID 37904225, 2023). "The transcription factor MYCN is frequently amplified and overexpressed in a variety of cancers including high-risk neuroblastoma (NB) and promotes tumor cell proliferation, survival, and migration." (PMID 37543638, 2023).
neuroblastoma (continued). "In this study, they established an immunocompetent mouse model for metastatic neuroblastoma which recapitulated not only overexpression of MYCN but also loss of Caspase-8 expression." (PMID 37274289, 2023). "We retrieved MYCN amplification status from eight neuroblastoma tumor datasets and assessed the association between NE score and MYCN expression while controlling for MYCN amplification." (PMID 37255415, 2023). "Our data highlight distinct circRNA expression profiles in risk groups, wherein circRNAs are least abundant in high-risk neuroblastomas harboring MYCN amplifications." (PMID 37402719, 2023). "High expression of MYCN is in about 20% of neuroblastomas and is associated with tumor progression and poor prognosis." (PMID 37592273, 2023). "Similar to other studies, ALK amplification occurred exclusively in MYCN-amplified neuroblastomas and were mutually exclusive with ALK point mutations." (PMID 36807339, 2023). "An independent prognostic nomogram, which included FRG risk, age, stage of the International Neuroblastoma Staging System, and an MYCN status, was constructed." (PMID 37521469, 2023). "At the molecular level, MYCN amplification independently indicates high-risk neuroblastoma that is associated with poor prognosis." (PMID 37958555, 2023). "The closely related c-MYC is also a potent transforming gene in a subset of high-risk neuroblastoma cases (∼10%) and feature of malignant progression in stage four non-MYCN-amplified tumours." (PMID 37414143, 2023). "Malignant expansion in neuroblastoma appears manly triggered by MYCN amplification or/and ALK and ATRX mutations." (PMID 37361539, 2023). "The international neuroblastoma risk group (INRG) classifies high-risk NB (NB-HR) as tumors with MYCN amplification, metastatic tumors in children over 18 months, or in those less than 18 months with 11q aberrations." (PMID 37024512, 2023). "Previously, using integrated neuroblastoma cohorts, we analyzed the transcriptional features of neuroblastoma associated with MYCN amplification and age at diagnosis ≥ 18 months." (PMID 35764946, 2022). "Neuroblastoma, the most common solid tumor in children, is characterized by amplification of the MYCN proto-oncogene, a high-risk aggressive clinical marker associated with treatment failure." (PMID 35805002, 2022). "Tumors with heterozygous loss of chromosome 11q and MYCN amplification are two genetically distinct subsets of neuroblastoma that are associated with poor patient outcome." (PMID 36237330, 2022). "Recently, the heterogeneity of neuroblastoma cells was defined by super-enhancer-associated transcription factors, such as MYCN and PHOX2B, and different tumor-cell subpopulations showed different characteristics of tumor development and metastasis." (PMID 35884407, 2022). "Elevated TERT expression is strongly associated with TERT promoter rearrangements or MYCN-amplification in neuroblastoma." (PMID 35406427, 2022). "MYCN, the human gene encoding N-Myc, was first identified as an oncogene amplified in human neuroblastoma, a tumor characterized as having undifferentiated neuroblasts." (PMID 34625907, 2022). "In Stage 4 non-MYCN amplified neuroblastoma patients, high TRPM2 expression is associated with worse outcome." (PMID 36446940, 2022). "SESN1 was downregulated in MYCN-amplified paediatric neuroblastoma patients, and SESN1 overexpression was associated with better clinical outcomes of paediatric neuroblastoma." (PMID 35655142, 2022). "The most frequent chromosomal aberrations associated with high-risk patients and poor prognosis in neuroblastoma are segmental gain of chromosome 17q, hemizygous loss of chromosome 1p and 11q, and somatically acquired amplification of the oncogene MYCN." (PMID 35362827, 2022).
neuroblastoma (continued). "Profiling of super enhancers and their target genes has led to molecular identification of super-enhancer-driven neuroblastoma subtypes that match known clinical groups, including MYCN-amplified, non-MYCN-amplified high-risk, and low-risk neuroblastoma tumors." (PMID 36077650, 2022). "Hyperdiploidy, genetic aberrations, and v-myc myelocytomatosis viral related oncogene (MYCN) amplification are among the most widely accepted genomic and genetic causes of neuroblastoma." (PMID 35574403, 2022). "Aberrant, increased expression of MYCN is also associated with other paediatric cancers such as neuroblastoma and medulloblastoma." (PMID 35729105, 2022). "The data suggest a differential immunogenic effect of PBNP-PTT on neuroblastoma cells in vitro, perhaps correlative with MYCN amplification and/or risk stratification." (PMID 35326601, 2022). "High-risk and MYCN amplified neuroblastoma present a different transcriptional profile, where different pathways and genes related to differentiation are particularly altered." (PMID 36139583, 2022). "Neuroblastoma cell lines with intermediate MYCN or MYC levels caused by gene translocations are known to exist." (PMID 35484422, 2022). "GLDC knockdown mitigates cell proliferation and tumorigenicity via causing G1 arrest in MYCN-amplified neuroblastoma cells." (PMID 36275705, 2022). "High-risk neuroblastoma is often manifested with MYCN amplifications, which is one of the most reliable prognostic factors." (PMID 36793342, 2022). "The INRG staging system implicates MYCN-amp as the criteria of high-risk neuroblastoma that requires aggressive treatment." (PMID 35681607, 2022). "JQ1 has been reported to cause human neuroblastoma cell cycle arrest in G1 phase mainly by inhibiting the MYCN and mTOR signaling pathways." (PMID 35902869, 2022). "In the SEQC/MAQC-III Consortium data, TFAP2B expression is decreased in stage 4 or metastatic neuroblastomas and low expression of TFAP2B is associated with worse event-free survival outcomes in non-MYCN amplified neuroblastoma patients." (PMID 35246212, 2022). "High expression of AHCY is associated with MYCN-amplified neuroblastoma and contributes to the enhanced proliferation of cancer cells." (PMID 36361596, 2022). "It is important to note that FOXR2 activity is associated with poor prognosis in neuroblastoma where it was shown to stabilize MYCN protein." (PMID 36337169, 2022). "MYCN oncogene amplification is associated with treatment failure and poor prognosis in neuroblastoma." (PMID 35820898, 2022). "Poor prognosis is linked to the dysregulation of polyamines in neuroblastoma, and various polyamine homeostasis-related genes are transcriptional targets of cMYC/MYCN." (PMID 36551330, 2022). "Disease progression is associated with amplification of the MYCN transcription factor in 20-30% of neuroblastomas." (PMID 36267982, 2022). "Surprisingly, we found that high pyroptosis neuroblastoma tends to have low expression of MYCN and a low score of myc target-related tumor hallmark." (PMID 35664308, 2022). "For instance, it has been shown that MYCN-overexpressing neuroblastoma cells were selectively susceptible to CDK7 inhibition by suppressing their MYCN-associated super-enhancers-associated genes." (PMID 36147741, 2022). "Here, we have shown that aryl sulfonamides are a viable and potent therapeutic strategy using multiple in vivo and in vitro neuroblastoma models including a transgenic mouse model of MYCN-driven, high-risk disease." (PMID 35296644, 2022). "N-Myc (encoded by MYCN), a transcription factor, is responsible for the growth of brain during embryogenesis and is a key oncogene in oncogenesis of neuroblastoma." (PMID 35633416, 2022). "Additional studies provide further evidence that elevated expression of MYCN is sufficient to drive high-risk neuroblastoma in various animal models." (PMID 36077650, 2022).
neuroblastoma (continued). "Further regression analyses suggested that bub1 expression was a risk factor irrelevant to MYCN amplification for the poor survival of neuroblastoma patients, supporting its role as an independent prognostic biomarker." (PMID 36237324, 2022). "EcDNA is linked to invasive tumor growth in many neuroblastomas, notably those expressing the MYCN oncogene." (PMID 35614494, 2022). "Further studies have employed computational approaches to identify the immunotherapy targets such as CAMKV in neuroblastoma patients presenting with MYCN or GPC2 amplification in high-risk neuroblastoma." (PMID 36295546, 2022). "A meta-analysis of primary neuroblastoma microarray data linked casein kinase I isoform epsilon (CK1ε) expression to MYCN amplification and poor prognosis." (PMID 35408915, 2022). "Along with the up-regulated AHCY, MYCN-amplified neuroblastoma cells have elevated levels of the CBS gene, encoding cystathionine beta synthase." (PMID 36361596, 2022). "Currently, blocking of the BET proteins is a widely used therapeutic strategy for MYCN amplified high-risk neuroblastoma." (PMID 36187481, 2022). "Retinoid-based multimodal differentiation therapy is one of the few interventions that extends relapse-free survival in MYCN-associated high-risk neuroblastoma and these results point toward the potential use of verlindamycin in this regimen." (PMID 34522028, 2022). "The copy numbers of MYCN are closely associated with the aggressiveness of neuroblastoma, with increased expression of MYCN that increases the proliferative potential of neuroblastoma cells." (PMID 34625907, 2022). "Current risk stratification of neuroblastoma patients is primarily based on clinical variables and molecular markers, such as genomic amplification of MYCN." (PMID 36153564, 2022). "In conclusion, we hereby present this novel inhibitory mechanism of verlindamycin as a potential therapeutic treatment of neuroblastoma, including MYCN-amplified high-risk subgroup, for the first time." (PMID 34522028, 2022). "On the other hand, some molecular alterations associated with neurological tumors have already been detected in plasma cfDNA, such as the number of MYCN copies in neuroblastoma or specific somatic mutations in glioblastoma (EGFR and IDH1)." (PMID 35563270, 2022). "Approximately 25% of patients with a neuroblastoma diagnosis present with MYCN amplification (MNA), which is linked to a poor prognosis, metastasis, and recurrence." (PMID 35490242, 2022). "For example, it can be applied in the prediction of the epidermal growth factor receptor mutation status in lung adenocarcinoma and MYCN amplification in neuroblastoma." (PMID 35204353, 2022). "More recently, other regulatory genes were investigated, including INSM1 that is activated by MYCN gene, expressed in a large fraction of neuroblastomas and associated to a shorter survival." (PMID 36121500, 2022). "MYCN amplification is associated with high-risk neuroblastoma, and is characterized as a genetic marker for neuroblastoma risk stratification." (PMID 35326601, 2022). "It was reported that hydroxyurea induced the overexpression of MDR1 in cells to reduce the expression of extrachromosomal MYCN, which provides a treatment target for the high-risk neuroblastoma in clinical settings." (PMID 36793345, 2022). "In neuroblastoma, MYCN amplification is associated with sparse immune infiltrate and poor prognosis." (PMID 36923280, 2022). "Our results were consistent with these observations that CCNE1 was upregulated in MYCN-amplified paediatric neuroblastoma patients, and CCNE1 overexpression was associated with worse clinical outcomes of paediatric neuroblastoma." (PMID 35655142, 2022). "Here, high TRPM2 expression was associated with significantly poorer outcome in Stage 4 non-MYCN amplified neuroblastoma patients using three publicly available databases." (PMID 36446940, 2022).
neuroblastoma (continued). "Neuroblastoma is the most common solid tumor in children featuring the amplification of the MYCN protooncogene, a high-risk aggressive clinical marker correlated with treatment failure." (PMID 35805002, 2022). "High-risk neuroblastoma (NB) often showed MYCN amplification and decreased susceptibility to the death of programmed cells induced by chemotherapy drugs." (PMID 35237304, 2022). "Higher expression of DLG2 was related to the survival of neuroblastoma patients, and it was negatively associated with MYCN status and tumor stage." (PMID 35111846, 2022). "The most aggressive subset of neuroblastoma has been associated with recurrent somatic mutations and with MYCN oncogene amplification, which can modulate antigens expressed in tumor cells and thus influence immune surveillance." (PMID 36923280, 2022). "Several molecular biomarkers associated with the occurrence and progression of neuroblastoma have been reported, including MYCN, a clinically recognized oncogenic transcription factor-related biomarker, anaplastic lymphoma kinase (ALK), and PHOX2B." (PMID 36237324, 2022). "As seen in other studies, the MYCN amplification is a prognostic factor and is usually associated with poorly differentiated or undifferentiated neuroblastoma." (PMID 36360435, 2022). "Structural genomic changes found in subsets of neuroblastoma, and linked to tumorigenesis and reduced survival, include MYCN amplification, ALK activating mutations, 1p36 deletion, or 17q gain." (PMID 34716856, 2022). "Neuroblastoma is the second most lethal solid tumor in children, and amplification of the MYCN-oncogene has been shown to be strongly associated with disease progression." (PMID 36114560, 2022). "Our previous results showed that E2F1 was a target of MYCN amplification and associated with the poor overall survival of neuroblastoma." (PMID 35764946, 2022). "Twenty percent of patients with neuroblastoma present with MYCN amplification, and many studies have linked MYCN amplification and ploidy, together with tumor histopathology, with prognosis in these patients." (PMID 36360435, 2022). "Further investigation identified SLC27A2, encoding FATP2, as a direct target gene of MYCN for transcriptional upregulation in neuroblastoma cells, leading to increased fatty acid uptake for glycerolipid synthesis." (PMID 36077650, 2022). "Clinical and preclinical studies have demonstrated that NEPC frequently involves the amplification of MYCN (encoding N-Myc, an oncogene associated with poor prognosis in neuroblastoma) and AURKA (Aurora-A)." (PMID 36135315, 2022). "Evaluation of miR-186-5p in publicly available datasets demonstrated lower expression of miR-186 in high-risk and MYCN amplified neuroblastoma and correlated with expression of NK activation markers, NKG2D and DNAM-1." (PMID 36793342, 2022). "Over 50% of patients have evidence of MYCN amplification and/or metastatic disease and are therefore considered to have high-risk neuroblastoma." (PMID 36097618, 2022). "Polyamines participate in many cellular processes governed by MYC genes, which have been identified as a hallmark of neuroblastomas with MYCN amplification." (PMID 35242701, 2022). "Overexpression of the MYCN gene causes cancer, specifically neuroblastoma, T-cell leukemia, glioblastoma, and breast adenocarcinoma." (PMID 36286044, 2022). "Aberrant MYCN activation, as a result of genomic MYCN amplification, is a major driver of high-risk neuroblastoma, which has an overall survival rate of less than 50%, despite the best treatments currently available." (PMID 36077650, 2022).